SIN3A (SIN3 transcription regulator family member A)
Description:
Acts as a transcriptional repressor. Corepressor for REST. Interacts with MXI1 to repress MYC responsive genes and antagonize MYC oncogenic activities. Also interacts with MXD1-MAX heterodimers to repress transcription by tethering SIN3A to DNA. Acts cooperatively with OGT to repress transcription in parallel with histone deacetylation. Involved in the control of the circadian rhythms. Required for the transcriptional repression of circadian target genes, such as PER1, mediated by the large PER complex through histone deacetylation. Cooperates with FOXK1 to regulate cell cycle progression probably by repressing cell cycle inhibitor genes expression (By similarity). Required for cortical neuron differentiation and callosal axon elongation (By similarity).
Synonyms: KIAA0700; DKFZP434K2235; CHR15DELq24; DEL15Q24; WITKOS
Tractability: PROTAC: UniProt records ubiquitination sites on it; ubiquitination databases record sites on it; its protein half-life has been measured.
Gene: Protein-coding gene on chromosome 15 (75,369,379 to 75,455,842, reverse strand). Ensembl gene ENSG00000169375.
Subcellular location: Nucleus; Nucleus, nucleolus
Subcellular location (Human Protein Atlas): Nucleoplasm
Pathways (Reactome):
Gene expression (Transcription): FOXO-mediated transcription of oxidative stress, metabolic and neuronal genes; NoRC negatively regulates rRNA expression; RUNX1 regulates genes involved in megakaryocyte differentiation and platelet function
Developmental Biology: Regulation of MITF-M-dependent genes involved in apoptosis; Regulation of MITF-M-dependent genes involved in cell cycle and proliferation
Cellular responses to stimuli: Cytoprotection by HMOX1
Hemostasis: Factors involved in megakaryocyte development and platelet production
Metabolism: Regulation of lipid metabolism by PPARalpha
Metabolism of proteins: SUMOylation of transcription cofactors
Signal Transduction: STAT3 nuclear events downstream of ALK signaling
Gene Ontology:
Molecular function: protein binding; RNA polymerase II-specific DNA-binding transcription factor binding; transcription corepressor activity; transcription regulator inhibitor activity; chromatin binding; DNA binding; protein-containing complex binding; RNA binding
Biological process: activation of innate immune response; heterochromatin formation; negative regulation of protein localization to nucleus; negative regulation of transcription by RNA polymerase II; positive regulation of defense response to virus by host; type I interferon-mediated signaling pathway; cerebral cortex neuron differentiation; negative regulation of cell migration; negative regulation of circadian rhythm; negative regulation of DNA-templated transcription; negative regulation of stem cell population maintenance; negative regulation of transcription initiation by RNA polymerase II; negative regulation of transforming growth factor beta receptor signaling pathway; positive regulation of neuron differentiation; positive regulation of stem cell population maintenance; regulation of axon extension; cellular response to dopamine; cellular response to tert-butyl hydroperoxide; regulation of DNA-templated transcription; regulation of hormone levels
Cellular component: histone deacetylase complex; nucleoplasm; nucleus; Sin3-type complex; chromatin; chromosome; kinetochore; nucleolus; protein-containing complex; transcription regulator complex; transcription repressor complex
Genetic constraint (gnomAD): Loss-of-function variants: 10 observed, 120.73 expected, observed/expected ratio (o/e) 0.0828, 90% interval 0.05 to 0.14. The upper end of that interval is the gene's LOEUF score, 0.14, which puts it in group 1 of 6, group 1 being the genes least tolerant of losing a copy. Missense variants: 905 observed, 1,442.3 expected, observed/expected ratio (o/e) 0.63, 90% interval 0.59 to 0.66. Synonymous variants: 513 observed, 534.46 expected, observed/expected ratio (o/e) 0.96, 90% interval 0.89 to 1.03.
Gene-disease validity (ClinGen):
ClinGen rates the evidence that SIN3A causes each of these diseases.
SIN3A-related intellectual disability syndrome (autosomal dominant): Definitive.
Homologues: Orthologues: chimpanzee SIN3A (99% identical), macaque SIN3A (99% identical), dog SIN3A (99% identical), pig SIN3A (99% identical), guinea pig SIN3A (99% identical), mouse Sin3a (98% identical), rat Sin3a (98% identical), rabbit SIN3A (92% identical), tropical clawed frog sin3a (83% identical), zebrafish sin3aa (78% identical), zebrafish sin3ab (75% identical), Drosophila melanogaster Sin3A (48% identical), and 1 more. Paralogues in human: SIN3B (48% identical).
Diseases named in the same sentence as SIN3A in open-access papers:
SIN3A is named in the same sentence as 74 diseases in open-access papers, as found by Europe PMC text mining. Sharing a sentence is not in itself a finding about the gene and the disease. The quoted sentences say what the papers report.
breast carcinoma (36 papers, 2010 to 2025). "In their study regarding breast cancer, Li and collaborators evaluated the pathophysiological function and underlying mechanism of FOXN3, a forkhead transcriptional repressor that is physically associated with the SIN3a complex in ER+ breast cancer cells." (PMID 38275371, 2023). "THRA has been found to be correlated with high breast cancer mortality, and SIN3A mutations in breast cancerenhances cell proliferation." (PMID 36124841, 2022). "For example, WES of breast cancer samples identified that the somatic mutation of SIN3A in breast cancer aggravated the tumor development." (PMID 34239995, 2021). "The scaffolding protein Switch-Independent 3A (SIN3A) has been implicated in breast cancer development." (PMID 31214487, 2019). "In tissue sections from the breast cancer patient with the SIN3A c.2830 C>T mutation, cytoplasmic SIN3A localization was detected within the tumor regions where nuclear enlargement was observed." (PMID 30375428, 2018). "Loss of SIN3A caused a significant increase in the number of invasive colonies in multiple human breast cancer cell lines, MDA-MB-231, MDA-MB-435, and MDA-MB-436." (PMID 29665841, 2018). "This is the first study to describe the novel somatic mutation of SIN3A c.2830 C>T; p.Gln944* that causes the deletion of the C-terminal region from Gln944 and contributes to cell proliferation in breast cancer." (PMID 30375428, 2018). "This larger dataset also uncovered significant prognostic value associated with PRMT8 and SIN3A as well as confirmed the well-known association of high EZH2 expression levels with poor survival in breast cancer." (PMID 27863398, 2016). "Knockdown of SIN3A caused an increase in the number of invaded cells, the presence of invasive colonies in 3D, and increased metastatic potential of breast cancer cells." (PMID 27780928, 2016). "Importantly, a truncated variant of Sin3A has been identified by exome sequencing of human breast cancer samples, indicating that Sin3A can function as a tumour suppressor in certain tissues." (PMID 36854981, 2023). "Three genes, TRADD, BNIP3L, and CASP9, increase in both cell lines with loss of Sin3A, demonstrating that Sin3A possesses some overlapping gene regulation between breast cancer cell lines, as may be expected." (PMID 20920219, 2010). "We carried out immunoprecipitation assays to assess whether, firstly, there exists a direct or indirect association between RARα, the RXRα heterodimer and Sin3A in breast cancer cell lines and, secondly, whether MAD1-SID treatment would disrupt this interaction." (PMID 35406744, 2022). "The cytoplasmic localization of the SIN3A mutant causes its loss of function resulting in cell proliferation, and the expression level of SIN3A mRNA may influence the survival curves for patients with breast cancers." (PMID 30375428, 2018). "Together, these results suggest that each subunit of homodimeric SAP30 respectively binds to MLL1 and SIN3A through F186/F200 residues in breast cancer cells." (PMID 37655663, 2023). "The role of SIN3a has been extensively investigated in the context of cancer, including melanoma, lung, and breast cancer." (PMID 38275371, 2023). "SIN3a has been extensively investigated in the context of various cancer types, including non-small-cell lung cancer, breast cancer, and colon cancer." (PMID 38275371, 2023). "SIN3A was suggested to affect breast cancer progression, and the correlation between SIN3A mRNA expression and the recurrence of ER-positive breast cancer was also raveled out." (PMID 35101035, 2022). "The LSD1/SIN3A/HDAC complex has been shown to regulate breast cancer cells' survival and carcinogenic potential and is required for epithelial homeostasis and chemotherapeutic sensitivity." (PMID 36476410, 2022).
breast carcinoma (continued). "They found that LSD1 was essential for breast cancer cell chemosensitivity, such as by coordinating with the SIN3A/HDAC complex and regulating a stem cell program." (PMID 36276611, 2022). "A recent comparative analysis demonstrated that in patients with breast cancer, a hypomethylation signature (OCT4, SOX2, NANOG and SIN3A) in CTC clusters is associated with poor progression-free survival." (PMID 34830995, 2021). "On the other hand, SIN3A is a transcriptional suppressor promoting osteolytic destruction in ERα-positive breast cancer." (PMID 35127514, 2021). "As potential upstream regulators of GOLT1B, JUN and SIN3A have been gained increasing attention in diagnosis and treatment of breast cancer." (PMID 35127514, 2021). "In breast cancer cells, interference with SIN3A function induces epigenetic reprogramming and differentiation, and the SIN3A/HDAC complex plays an important role in maintaining sensitivity to chemotherapy in breast cancer." (PMID 33232269, 2020). "Recently, binding sites for OCT4, NANOG, SOX2 and SIN3A in breast cancer CTC clusters were shown to be hypomethylated to what is seen in embryonic stem cell biology." (PMID 30875950, 2019). "The breast cancer tissue containing SIN3A p.Gln944* showed a 1.6-fold higher expression level of ESR1 mRNA than breast cancer tissues containing SIN3A-WT." (PMID 30375428, 2018). "We focused on the relationship between the nonsense point mutation c.2830 C>T; p.Gln944* in SIN3A and ESR1 expression in breast cancer cells, because SIN3A, which is coded by the gene for SIN3A, works as a transcriptional repressor of ERα as reported." (PMID 30375428, 2018). "In the breast cancer tissue positive for SIN3A c.2830 C>T, the SIN3A protein appeared to be decreased as compared with SIN3A-WT." (PMID 30375428, 2018). "The transcriptional regulation of SIN3A in luminal subtype breast cancers would provide a new therapeutic target for breast cancers." (PMID 30375428, 2018). "Of the somatic mutations validated by a different deep sequencer, a novel nonsense somatic mutation, c.2830 C>T; p.Gln944*, in transcriptional regulator switch-independent 3 family member A (SIN3A) was detected in breast cancer of a patient." (PMID 30375428, 2018). "Of the transcriptional regulators, GATA2, PHF1 and SIN3A were previously reported to be involved in breast cancer." (PMID 30375428, 2018). "When all breast cancer subtypes were considered, longer relapse-free survival of patients correlated with high expression of either SIN3A or SIN3B." (PMID 29665841, 2018). "The level of SIN3A mRNA expression in the breast cancer tissue with SIN3A c.2830 C>T appeared to be lower than in those with SIN3A-WT, and SIN3A mRNA in the SIN3A mutant samples included approximately 20% SIN3A mutant sequence (data not shown)." (PMID 30375428, 2018). "The results suggest that SIN3B is required for and is a promoter of breast cancer progression and metastasis, and further suggest that SIN3A is a metastasis suppressor." (PMID 27780928, 2016). "Together, these results demonstrate differential regulation of breast cancer cell invasion by SIN3A and SIN3B." (PMID 27780928, 2016). "Here, we show that individual knockdown of SIN3A causes an increase, whereas knockdown of SIN3B causes a decrease in breast cancer invasion and metastatic potential." (PMID 27780928, 2016). "High expression of either SIN3A or SIN3B correlated with longer relapse-free survival in all breast cancers (hazard ratios = 0.58 and 0.49; logrank P = 7.8e-10 and < 1e-16 respectively for SIN3A and SIN3B)." (PMID 27780928, 2016). "Our identification of Sin3A as a prosurvival factor is further interesting in that it highlights the importance of estrogen-mediated survival of breast cancer cells." (PMID 20920219, 2010).
breast carcinoma (continued). "In sum, the loss of HDAC1 and HDAC2 increases C3 and NCOA2, but not CLU, ERBB2, MYC, or PGR, providing evidence that C3 and NCOA2 are repressed in breast cancer cells by the HDAC1/2 components of the Sin3A repressive complex." (PMID 20920219, 2010). "We previously showed that Sin3A is expressed in breast cancer cells and is a repressor of estrogen receptor-alpha (ERα, ESR1) gene expression." (PMID 20920219, 2010). "This led us to further determine Sin3A regulation of gene expression and growth in breast cancer cells." (PMID 20920219, 2010). "Flow cytometry analysis was performed on Sin3A knockdown cells to determine the role of Sin3A in cell cycle progression of breast cancer cells." (PMID 20920219, 2010). "Here, we expand our previous studies to elucidate the function of Sin3A in the control of gene expression and growth of breast cancer cells." (PMID 20920219, 2010). "Our findings show that Sin3A is a prosurvival protein that promotes growth of ERα-positive breast cancer cells by preventing apoptosis through repression of key proapoptotic genes." (PMID 20920219, 2010). "In this report, we expand our previous findings and identify the function of Sin3A in gene expression, survival, and growth of breast cancer cells." (PMID 20920219, 2010). "This is one of the first studies to analyze the role of the Sin3A transcriptional repressor protein in breast cancer." (PMID 20920219, 2010). "This study identifies Sin3A as a regulator of gene expression, survival, and growth in ERα-positive breast cancer cells." (PMID 20920219, 2010). "Cell growth assays were performed to determine if the observed increase in apoptosis by Sin3A knockdown was sufficient to attenuate growth of breast cancer cells." (PMID 20920219, 2010). "This study identifies the transcriptional repressor, Sin3A, as a necessary survival factor in ERα-positive breast cancer cells." (PMID 20920219, 2010). "SAP30 promotes breast cancer progression in a SIN3A/3B-dependent manner." (PMID 37655663, 2023). "To determine whether the SIN3 complex mediates breast cancer progression, we knocked out both SIN3A and SIN3B proteins with the CRISPR/Cas9 technique in MDA-MB-231 cells." (PMID 37655663, 2023). "Moreover, LSD1 coordinates with the SIN3A/HDAC complex to maintain sensitivity to chemotherapy in breast cancer." (PMID 37291119, 2023). "Breast cancer cells require SIN3A for survival and development." (PMID 36476410, 2022). "Besides, SIN3A is not only necessary for the survival and proliferation of breast cancer cells but also essential for maintaining epithelial stability and chemical sensitivity, and is one promising drug target for breast cancer treatment." (PMID 35127514, 2021). "No nonsense or frameshift mutations resulting in the deletion of the C-terminus of SIN3A were detected in triple negative (n = 141) or Her2-positive breast cancers (n = 72)." (PMID 30375428, 2018). "The interaction of FOXK2 may be prevented by the cytoplasmic localization of SIN3A p.Gln944*, and thus may cancel the growth inhibition of breast cancer cells." (PMID 30375428, 2018). "Our data supports SIN3A as a suppressor of breast cancer progression and metastasis, whereas SIN3B may be a promoter." (PMID 27780928, 2016). "However, knockdown of SIN3A in estrogen receptor positive (ER+) breast cancer cell lines resulted in increased apoptosis and attenuation of cell growth that was not identified in ER negative breast cancer cell lines." (PMID 27780928, 2016). "The role of Sin3A in breast cancer is virtually unexplored, but studies suggest that Sin3A is important in normal growth and may be a player in other neoplastic model systems." (PMID 20920219, 2010). "Loss of Sin3A inhibited breast cancer cell growth by increasing apoptosis without affecting cell cycle progression." (PMID 20920219, 2010).